USP10 (ubiquitin specific peptidase 10)
Diseases named in the same sentence as USP10 in open-access papers (continued):
Sharing a sentence is not in itself a finding about the gene and the disease.
tumor (93 papers, 2011 to 2026). "While some studies have established USP10's tumor-promoting functions across various cancer types, the precise molecular mechanisms underlying USP10's role in NPC pathogenesis remain to be fully elucidated." (PMID 41522354, 2026). "Analysis of TCGA data indicated that USP10 is highly expressed in tumor tissues and is associated with poor prognosis." (PMID 41522354, 2026). "Four weeks later, we found that loss expression of USP10 significantly retarded the tumor growth in vivo." (PMID 40464594, 2025). "In summary, our study showed that USP10 was a tumor promoter and explored the underlying mechanism of USP10 in PDAC." (PMID 40517136, 2025). "Here, we demonstrated that increasing ULK1 expression through USP10 upregulation rendered OS cells more susceptible to autophagy and tumor development." (PMID 39218913, 2024). "Given that the super competitor signalling cascade leads to the secretion of signalling molecules initiating cell death, loss of USP10 controls extrinsic signalling mechanisms and thereby opposes tumour growth." (PMID 39443725, 2024). "Extensive studies indicated that USP10, as a deubiquitinating enzyme, is associated with the growth of tumor cells and play an important role in various cancers." (PMID 37919637, 2023). "NLRP7 deubiquitination by USP10 promotes tumor progression and tumor-associated macrophage polarization in CRC." (PMID 36874086, 2023). "Given the homologous data in GEPIA and TIMER from the TCGA, we used the GEPIA database to further assess the associations between the expression of USP10 and markers genes of monocytes and TAMs in tumor tissues of PAAD, LIHC, and LUAD." (PMID 35433424, 2022). "Noticeably, almost all the tumor cases with genetic alterations had deletions or mutations of USP10." (PMID 35433424, 2022). "USP10 expression was also associated with tumor aggressiveness." (PMID 40991650, 2025). "Furthermore, loss of USP10 led to enriched gene sets associated with stress signalling, such as unfolded protein response and reactive oxygen species signalling in P6T tumour organoids." (PMID 39443725, 2024). "Loss of USP10, while resulting in tumour organoid engraftment, led to smaller lesions." (PMID 39443725, 2024). "By contrast, USP10 is closely associated with tumor immunity." (PMID 35433424, 2022). "However, the pan-cancer expression pattern of USP10, its prognostic value, and the association between tumor immune cell infiltration and USP10 expression remain to be discussed and thus comprised the aims of the present study." (PMID 35433424, 2022). "Meanwhile, in certain cancers, increased USP10 expression is associated with tumor suppression." (PMID 36248971, 2022). "Our data clearly confirm that USP10 expression is positively associated with lymph node metastasis, which supports that USP10's association with outcome may partially reflect its dual roles in both tumor cellular biology and metastasis." (PMID 40605431, 2025). "Thus, USP10 inhibitors may be clinically useful in cancer settings where overexpression of USP10 is associated with tumor progression or in settings where USP10 serves as an oncogene." (PMID 36248971, 2022). "A significant upregulation of MRPS7, MRPS23, and USP10 was observed in tumor tissues relative to matched adjacent non-tumor tissues." (PMID 41522354, 2026). "Mechanistically, USP10 drives tumor progression through multiple molecular axes, each contributing to distinct oncogenic processes." (PMID 41522354, 2026).
tumor (continued). "The tumor-specific biological context significantly influences the diverse functions and regulatory mechanisms of USP10 in tumorigenesis and cancer progression." (PMID 41522354, 2026). "To evaluate the role of USP10 in tumor growth in vivo, we utilized a subcutaneous xenograft mouse model." (PMID 41522354, 2026). "Knockdown of USP10 significantly suppressed tumor growth, as evidenced by reduced tumor volume and mass, and decreased Ki-67 staining, indicating lower proliferative activity." (PMID 41522354, 2026). "Pharmacological inhibition of USP10 using spautin-1 synergized with cisplatin, significantly suppressing tumor growth in preclinical models." (PMID 41522354, 2026). "In our study, we demonstrated that pharmacological inhibition of USP10 using spautin-1 synergistically enhances the anti-tumor efficacy of cisplatin, significantly suppressing tumor growth and lung metastasis in preclinical mouse models." (PMID 41522354, 2026). "These USP10 substrates contain both tumor suppressors and oncogenic proteins, thus conferring both inhibitory and promoting effects of USP10 on tumorigenesis and progression." (PMID 41892309, 2026). "To test if USP10 is correlated with PI3Ki resistance in PDX tumors that exhibit high AKT activation, we explored the expression of USP10 in these tumor samples." (PMID 40991650, 2025). "In summary, we revealed that USP10, as a tumor promoter, promoted the progression and attenuated GEM chemotherapy sensitivity via stabilizing PLK1 in PDAC, providing a potential target for the treatment of PDAC." (PMID 40517136, 2025). "AGD1 mediates the stemness and apoptosis of PCSCs and promotes docetaxel treatment resistance by enhancing tumor growth and metastasis through USP10/METTL13-mediated CD44 mRNA decay in CRPC." (PMID 39806412, 2025). "The findings demonstrated that the control group exhibited a higher growth rate and tumor weight than the USP10 knockdown group." (PMID 40517136, 2025). "Overall, tumour cells derived from shNTC organoids showed an enriched abundance of USP10 and β-Catenin, which is in line with our previous observations." (PMID 39443725, 2024). "Pharmacological inhibition of USP10 promotes the degradation of B7‐H4, enhancing tumor immunogenicity and consequently improving the tumor‐killing efficacy of SG." (PMID 39206932, 2024). "Analysing publicly available patient data and samples from local CRC patients, we found that USP10 is frequently upregulated in human CRC tumours and is often co-expressed with β-Catenin." (PMID 39443725, 2024). "For example, the upregulation of miR-103 in PDAC leads to increased tumor metastasis and a poor prognosis through regulating target USP10 (ubiquitin-specific peptidase 10)." (PMID 38612727, 2024). "USP10 plays a critical role in tumor cell proliferation, metastasis, apoptosis, metabolism, and cancer progression by deubiquitinating a diverse array of substrates." (PMID 39218913, 2024). "In preclinical TNBC models, suppression of USP10/B7‐H4 proteolytic axis is effective in increasing SG killing efficacy and reducing tumor growth, especially for the tumors with the USP10high/B7‐H7high signature." (PMID 39206932, 2024). "This is in line with the observation that NOTUM was downregulated in patient derived CRC tumour organoids upon silencing of USP10." (PMID 39443725, 2024). "Mechanistically, the inhibition of autocrine motility factor receptor (AMFR)‐mediated ubiquitylation of B7‐H4 by the deubiquitinase USP10 leads to the stabilization of B7‐H4, which suppresses tumor immune activity and reduces SG treatment effectiveness." (PMID 39206932, 2024). "Similar to the observation in patent-derived primary resected CRC tumours, the endogenous protein levels of USP10 was significantly increased in tumour derived organoids, compared to non-oncogenic." (PMID 39443725, 2024). "In contrast, mice injected with USP10‐KD cells displayed significantly inhibited tumor growth and reduced tumor weight compared to the control group." (PMID 39206932, 2024).
tumor (continued). "We tested this observation in human and murine intestinal wild type and tumour organoid models regarding the regulation of USP10." (PMID 39443725, 2024). "Overall, our results demonstrate that USP10 plays a critical role in regulating B7‐H4, which, in turn orchestrates tumor immune evasion by stabilizing protein expression through deubiquitylation." (PMID 39206932, 2024). "USP10 acts as either a tumor suppressor or oncogene in a manner dependent on the function of its substrates." (PMID 39314885, 2024). "In vivo, tumor growth was inhibited following USP10 knockdown, with lower tumor weights and volumes were observed in the shUSP10 group compared to the shNC or shUSP10 + ULK1 groups." (PMID 39218913, 2024). "To validate that the USP10-mediated tumor-promoting effects were dependent on FOXC1, we conducted a series of functional experiments." (PMID 39430239, 2024). "Loss of USP10 reduced NOTUM signalling, a prerequisite for competitive tumour cell growth, and prevented tumour engraftment and growth in vivo." (PMID 39443725, 2024). "CircHAS2 and USP10 co-localized at the tissue level in tissue microarrays containing 70 CRC tumor samples and matched adjacent normal tissues." (PMID 38515149, 2024). "Using a xenograft mouse model, we showed that Spautin-1, a small-molecule inhibitor targeting USP10, significantly reduced OS development, with its anti-tumour activity significantly enhanced when combined with the chemotherapeutic agent cisplatin." (PMID 39218913, 2024). "Research has indicated that USP10 plays a crucial part in the advancement of tumors, encompassing tumor invasion, spread to other parts of the body, and the prediction of the disease's outcome." (PMID 39517125, 2024). "Stabilization of B7‐H4 by USP10 enhances the “cold” tumor environment and potentially reduces the therapeutic efficacy of SG." (PMID 39206932, 2024). "To investigate the clinical relevance and dependency of human CRC tumours towards USP10 in a patient-relevant setting, we used patient-derived organoids." (PMID 39443725, 2024). "Inhibiting USP10 shifts the balance, restores B7‐H4 turnover, revives tumor immunogenicity, and enhances the therapeutic impact of sacituzumab govitecan." (PMID 39206932, 2024). "Collectively, our results showed that USP10 stimulates OS autophagy and tumor progression by upregulating the GSK3β-ULK1 axis." (PMID 39218913, 2024). "USP10 also affects cell fate and tumor progression via the regulation of autophagy, deubiquitinating LC3B to stabilize its protein levels." (PMID 39218913, 2024). "Our endeavor on multiomic analyses coupled with experimental validation has drawn attention to the USP10/B7‐H4 proteolytic axis as a possible pivotal target to potentiate tumor immune response and augment ADC efficacy in treating immune‐cold TNBCs." (PMID 39206932, 2024). "Overexpression of USP10 correlated with tumor size, distant metastasis, and TNM stage, and was an independent factor of poor prognosis in OS patients." (PMID 37184153, 2023). "To clarify the link between USP10 and RUNX1 in GBM subtypes, we constructed a heatmap for the expression markers of GBM-associated tumor markers across GBM types." (PMID 36949071, 2023). "For examining the impacts of USP10 on OS in vivo, we constructed a tumor xenotransplantation model, in which the shUSP10 OS cells were subcutaneously inoculated and administrated into the tail vein of nude mice, respectively." (PMID 37184153, 2023). "In summary, N1DARP suppresses tumor initiation, progression, and chemosensitivity by competitively impeding USP10-mediated deubiquitination and stabilization of N1ICD." (PMID 37714834, 2023). "Histologically, H&E staining showed that the USP10-overexpressing xenografts displayed rampant tumor growth, whereas this effect was reversed by inhibition of RUNX1." (PMID 36949071, 2023).
tumor (continued). "Overall, these studies demonstrated that USP10 targets the PTEN/AKT/mTOR signaling pathway in NSCLC by preventing K63-linked polyubiquitination of PTEN and, thus, acts as a tumor suppressor." (PMID 37631304, 2023). "In a study, He and colleagues determined the effect and mechanism of USP10 as a tumor suppressor Dub of PTEN." (PMID 37631304, 2023). "Since USP10 positively regulates oncoproteins, it is more likely to act as a tumor-promoting factor for ESCC." (PMID 36526897, 2023). "Tumor and adjacent tissues were subjected to qRT‐PCR and western blotting, and the findings confirmed that USP10 was highly expressed in OS tissues." (PMID 37184153, 2023). "The expression of USP10 was correlated with tumor size, distant metastasis, and TNM stage in OS patients." (PMID 37184153, 2023). "Treatment with SAH-mAH2-5, which had a synergistic effect with GEM, suppressed tumor growth and extended the survival of mice, especially those with higher USP10 and N1ICD expression." (PMID 37714834, 2023). "USP10 facilitates tumor migration by stabilizing the protein abundance of the EMT transcription factor Slug." (PMID 35627217, 2022). "USP10 has been reported to deubiquitylate NLRP7 at Lys379 to enhance its stability and expression to promote tumor progression and tumor associated M2 macrophage polarization in colorectal cancer." (PMID 35800898, 2022). "In this review, we summarize the downstream substrates and upstream regulators of USP10 as well as its dual role as an oncogene and tumor suppressor in various human cancers." (PMID 35627217, 2022). "USP10 acts as a tumor suppressor or tumor-promoting gene depending on the target genes modified by deubiquitination." (PMID 36248971, 2022). "Normal breast, colon, kidney, and skin tissue samples showed weak USP10 staining, while tumor tissues showed intense staining." (PMID 35433424, 2022). "All these results indicate that in the same cancers, USP10 affects tumor development via regulating different substrates." (PMID 35627217, 2022). "In this paper, we have discussed the biological function of USP10 and its key role in tumor progression and immune response." (PMID 36248971, 2022). "Normal lung, prostate, and liver tissues showed moderate USP10 IHC staining, whereas tumor tissues showed intense staining." (PMID 35433424, 2022). "In malignancies such as gastric carcinomas, hepatocellular carcinoma, and intestinal adenocarcinomas, USP10 is suggested to play a tumor suppressing role." (PMID 36543867, 2022). "The overexpression of USP10 can inhibit the formation of stress granules (SGs), thus restraining the development of a tumor." (PMID 35627217, 2022). "Accumulating evidence demonstrated that USP10 play crucial roles as a tumor-promoter or tumor-suppressor in the tumorigenesis and development of various cancers." (PMID 35351136, 2022).
tumor (continued). "USP14 is also a well-known tumor promoter similar to USP10 which contains USP domain in C-terminal and ubiquitin-like (UBL) domain in N-terminal to regulate proteasomal activity, and BL1 and BL2 domains are also key factors for USP14 activity." (PMID 36582601, 2022). "USP10 is also involved in a wide range of biological functions such as environmental stress responses, tumor growth, inflammation, and cellular metabolism." (PMID 34967276, 2022). "USP10 gene mutations were observed in numerous cancers; therefore, we next explored the potential relationship between the tumor mutational burden (TMB) and USP10 expression in the clinical survival prognosis of different types of cancer." (PMID 35433424, 2022). "In summary, this review outlines the role of USP10 in various forms of cancer, discusses the relevance of USP10 inhibitors in anti-tumor therapies, and highlights the potential function of USP10 in regulating the immune responses of tumors." (PMID 36248971, 2022). "The relationship between the abnormal expression of USP10 in various tumors and its regulation of immune pathways prompted us to explore the role of USP10 in tumor development and immunity." (PMID 36248971, 2022). "USP10 exerts diverse functions on tumor progression, and the oncogenic or oncostatic function of USP10 was largely dictated by its substrate(s) in the specific cellular context of cancer models." (PMID 36163081, 2022). "Tumor xenograft experiments showed that NLRP7 or USP10 knockdown inhibited the growth of HCT116 tumors in vivo, whereas overexpression of NLRP7 in USP10 knockdown cells had a synergistic effect on tumor growth." (PMID 33838681, 2021). "Ubiquitin-specific peptidase 10 (USP10) is a protease that acts as an anti-stress factor and tumor-suppressor enzyme during cancer and regulates cellular metabolism." (PMID 33622377, 2021). "Numerous tumor suppressors and oncogenic proteins have surfaced as USP10’s substrates, and the list of these substrates is still rapidly growing." (PMID 34746935, 2021). "Collectively, the in vitro and in vivo results suggest that NLRP7 is involved in the effect of USP10 on promoting tumor progression and metastasis in CRC." (PMID 33838681, 2021). "CAPRIN-1 and USP10 not only have opposite effect on SGs regulation, but also have opposed incidence on cell proliferation and tumor development." (PMID 32882814, 2020). "The preceding studies show that USP10 can act as a tumor suppressor via specific cellular mechanisms." (PMID 33277473, 2020). "Epithelial–mesenchymal transition (EMT) plays fundamental roles in the early metastatic tumor by endowing tumor cells with a more motile and invasive potential, so we firstly examined the effect imposed by USP10 on EMT‐relevant proteins." (PMID 31721429, 2020). "To investigate the effect of USP10 knockdown on tumor growth in vivo, we inoculated four pairs of control and USP10 knockdown cancer cells, H23, H1299, SKOV3, and ES-2 in immune-deficient mice and measured xenograft growth in a time course." (PMID 32382008, 2020). "USP10 is involved in environmental stress responses, tumour growth, inflammation, and cellular metabolism." (PMID 33133065, 2020). "Knockdown of USP10 drastically reduced xenograft growth, and in combination with cisplatin treatment almost completely abolished tumor initiation." (PMID 32382008, 2020). "We observed that tumor weight and volumes in the USP10 knockdown group were significantly decreased compared with the scramble group." (PMID 31044085, 2019). "We also detected and compared the expressional level of USP10 in NSCLC tumor tissue and the respective adjacent normal lung tissue from 18 cancer patients." (PMID 27003362, 2016).